PRTN3 (proteinase 3)
Diseases named in the same sentence as PRTN3 in open-access papers (continued):
Sharing a sentence is not in itself a finding about the gene and the disease.
emphysema (10 papers, 2013 to 2024). "Higher aPWV was associated with impairments in lung physiology, the presence of emphysema on CT scan and proteinase 3 activity following adjustment for age, smoking status and traditional CVD risk factors (using QRISK2® scores) in AATD." (PMID 38515138, 2024). "It was reported that patients that lack alpha-1 antitrypsin (α1-Pi) which is the physiological inhibitor of PRTN3 and ELANE carries a high risk of developing emphysema." (PMID 33079950, 2020). "The PI*F allele has a reduced functional ability to inhibit neutrophil elastase but not proteinase 3, suggesting that inheritance of the F variant may increase a person's susceptibility to elastase-induced lung damage, but not necessarily to emphysema." (PMID 37277845, 2023). "Subsequent work has shown that other proteolytic enzymes contained in neutrophil granules such as proteinase 3 and cathepsin G also have the potential to induce many of the pathological changes observed in COPD, not just emphysema." (PMID 24229090, 2013).
periodontitis (10 papers, 2014 to 2023). An acute or chronic inflammatory process that affects the tissues that surround and support the teeth. "Our results demonstrated that GCF proteinase 3 total amounts in periodontitis and gingivitis groups were significantly higher compared to healthy control but similar among the diseased groups." (PMID 24949444, 2014). "In the present study GCF proteinase 3 levels were significantly higher in both periodontitis and gingivitis groups compared to healthy controls." (PMID 24949444, 2014). "Studies evaluating proteinase inhibitors together with proteinase 3 in periodontitis and gingivitis would provide information about the role of this enzyme in the periodontal pathogenesis." (PMID 24949444, 2014). "Similarly, in our previous study, it was presented that proteinase 3 levels in GCF were increased in patients with periodontal tissue loss in comparison to healthy controls, but similar between periodontitis and gingivitis subjects." (PMID 32748292, 2020). "After adjusting for age, periodontitis and gingivitis groups had significantly higher GCF proteinase 3 total amounts compared to healthy control group (P < 0.05)." (PMID 24949444, 2014). "The present study demonstrated that proteinase 3 total amounts were significantly higher in periodontitis and gingivitis groups than healthy controls but not significantly different among the diseased groups." (PMID 24949444, 2014). "Taken together it might be suggested that defects in or the secretion of azurophilic granules of neutrophils is partly responsible for not significantly elevated levels of GCF proteinase 3 in periodontitis groups more than in gingivitis groups." (PMID 24949444, 2014).
autoimmune hepatitis (9 papers, 2014 to 2025). Hepatitis caused by autoantibodies. "There was no agreement between ANCA patterns and antigenic specificities in IBD and autoimmune liver diseases, which reinforces the need for proteinase-3 and myeloperoxidase antibody testing." (PMID 33567045, 2021).
bronchiectasis (9 papers, 2019 to 2025). Segmental, irreversible dilation of the bronchial tree resulting in the accumulation of secretions which leads to obstruction. "An imbalance between neutrophil-derived serine proteases (NSPs) (neutrophil elastase (NE), proteinase 3 (PR3) and cathepsin G (CatG)) and their inhibitors has been implicated in many chronic inflammatory respiratory diseases, including bronchiectasis." (PMID 37465817, 2023). "The excessive release of neutrophil serine proteases, such as neutrophil elastase, cathepsin G and proteinase 3, promotes a protease–antiprotease imbalance that correlates with increased inflammation in bronchiectasis and contributes to disease progression." (PMID 40174958, 2025). "Neutrophilic inflammation and an imbalance between neutrophil-derived serine proteases (NSPs; neutrophil elastase (NE), proteinase 3 (PR3) and cathepsin G) and their anti-proteases are central features of bronchiectasis." (PMID 38529344, 2024). "In addition to NE, neutrophils secrete other NSPs, including cathepsin G (CatG) and proteinase 3 (PR3), which contribute to the pathophysiology of bronchiectasis by increasing inflammation further, leading to structural damage and promoting infection." (PMID 40753522, 2025).
Sepsis (9 papers, 2012 to 2025). Sepsis is defined as life-threatening organ dysfunction caused by a dysregulated host response to infection. "Although molecules such as MMP9 and PRTN3 have also been linked to sepsis prognosis, current investigations into these molecules in sepsis remain limited." (PMID 41305822, 2025). "Sivelestat, a selective ELANE and PRTN3 inhibitor was shown to improve the mortality rates of patients with sepsis associated with acute respiratory distress syndrome and disseminated intravascular coagulation." (PMID 33374674, 2020). "Prior time series analysis of septic patients identified three genes in the elastase family (ELANE, CTSG, PRTN3) and DEFA4 as candidate biomarkers for sepsis, while other studies likewise implicated NETosis genes including ALPL." (PMID 41385588, 2025). "However, there were no changes in the expression levels of CTSC, CTSG, PRTN3 and ELANE in neutrophils during sepsis compared to those from healthy controls." (PMID 33868254, 2021).
colitis (8 papers, 2014 to 2023). Inflammation of the colon. "Elafin is an endogenous specific inhibitor of neutrophil elastase (NE) and proteinase 3, and we previously found Elafin can effectively suppress the development of colitis." (PMID 35602072, 2022). "The mRNA expression levels of the serine proteases cathepsin G, proteinase 3 and neutrophil elastase were upregulated, while matriptase and urokinase were downregulated and tryptase αβ1 and tryptase β2 were unaltered in colitis compared to control animals." (PMID 34248633, 2021). "Future studies have to show whether colitis-like symptoms can also be evoked through exposure to autoantigens, such as proteinase 3 (PR3) detected by pANCAs, which have been identified as a biological marker of UC." (PMID 27491073, 2016).
infective endocarditis (8 papers, 2019 to 2025). Infective endocarditis (IE) is an infection of the inner lining of the heart chambers (endocardium) and valves. "ANCA positivity has been reported in a small cohort of subjects with infective endocarditis, particularly directed towards proteinase 3 (PR3-ANCA)." (PMID 37762758, 2023). "We report a case of a 46-year-old Han Chinese man with untreated chronic hepatitis B virus infection who featured proteinase-3 antineutrophil cytoplasmic antibody positivity while hospitalized with infective endocarditis." (PMID 32624005, 2020). "We believe that an accumulation of histological findings and treatments is mandatory for establishment of optimal management for proteinase 3-antineutrophil cytoplasmic antibody-positive renal injury complicated with infective endocarditis." (PMID 31801609, 2019).
primary sclerosing cholangitis (8 papers, 2014 to 2025). "A highly sensitive detection of anti-neutrophil cytoplasmic antibodies to serine proteinase-3 (PR3-ANCAs) aids in the serological diagnosis of autoimmune liver disorders and the prediction of severity in primary sclerosing cholangitis (PSC)." (PMID 36359524, 2022).
type 2 diabetes (8 papers, 2015 to 2025). "Neutrophil serine proteases, which are crucial components of NET, including neutrophil elastase (NE) and proteinase 3 (PR3), have been shown to participate in the initiation of insulin resistance and type 2 diabetes." (PMID 32377527, 2020). "Moreover, PRTN3 has been proposed as an inflammatory enzyme able to digest insulin-like growth factor 1 (IGF-1) and the insulin-like growth factor-binding protein-3 (IGFBP3) and promote glomerular inflammation in type 2 diabetes." (PMID 25874235, 2015).
fungal infection (7 papers, 2020 to 2025). "For example, neutrophils are considered the principal source of proteinase 3, which processes IL-1β, during the acute bacterial and fungal infection." (PMID 33644037, 2020).
polyarteritis nodosa (7 papers, 2009 to 2024). Polyarteritis nodosa (PAN) is a rare, clinically heterogeneous, rheumatologic disease characterized by necrotizing inflammatory lesions affecting small- and medium-sized blood vessels. "Serology will be positive for anti-proteinase 3(Antineutrophil cytoplasmic antibody) which is highly specific for W G. The differential diagnosis for WG includes polyarteritis nodosa, Churg-Strauss, Henoch-Schonlein purpura, temporal arteritis and Takayasu syndrome." (PMID 20066062, 2009). "Antineutrophil cytoplasmic antibodies (ANCA), including proteinase 3- (PR3-) ANCA and myeloperoxidase- (MPO-) ANCA, were negative and hepatitis B virus (HBV) antigen (HBs antigen) and antibody (HBs antibody) which suggest the possibility of polyarteritis nodosa were also not detected." (PMID 27034879, 2016).
asthma (6 papers, 2011 to 2025). "PRTN3 encodes for an airway biomarker associated with neutrophil activation and poor asthma control." (PMID 38540988, 2024).
atherosclerosis (6 papers, 2018 to 2025). A disease characterized by the build-up of fatty material and calcium deposition in the arterial wall resulting in partial or complete occlusion of the arterial lumen. "By inhibiting the expression of membrane-associated protein A1, PRTN3 eventually promoted atherosclerosis-related inflammatory responses." (PMID 39609876, 2024). "The protein encoded by the PRTN3 gene is one of the main components of neutrophils and is involved in the activation and processing of pro-inflammatory cytokines associated with atherosclerosis, such as IL-1β, TNF-α, and MCP-1." (PMID 39609876, 2024). "Increasing evidence using different strategies (i.e., pharmacologically blocking NET formation, genetic deletion of NE and proteinase 3, etc.)suggests that NETs may play an important role in driving atherosclerosis." (PMID 30140264, 2018). "A significant downregulation was also seen for myeloperoxidase (MPO), azurocidin (AZU) and proteinase 3 (PRTN3), which are all atherosclerosis biomarkers." (PMID 38715599, 2024).
breast carcinoma (6 papers, 2020 to 2025). "Moreover, ICAM3, CCL16, PDE3A, PRTN3, TRAF6, BCAR1, IL-1α, IL-1β, NFκB1, SOX2 and OCT4 decreases the protein expression as indicated by immunofluorescence staining in the ibuprofen-treated MDA-MB-231 breast cancer cells versus the control." (PMID 32528119, 2020).
Hepatic steatosis (6 papers, 2019 to 2025). Steatosis is a term used to denote lipid accumulation within hepatocytes. "Therefore, increased abundance of 0-Gran-Wfdc17, elevated levels of neutrophil serine proteases (NE, PRTN3 and Cathepsin G), and upregulated genes enriched in NETs formation are involved in the aggravation of fatty liver caused by loss of ApoA4." (PMID 36426356, 2022). "Importantly, experimental models have shown that PRTN3 is upregulated in the steatotic liver of obese mice, while PRTN3 knockout prevents hepatic steatosis and insulin resistance." (PMID 40822952, 2025). "The identification of these protein hubs may reflect underlying pathways involved in dyslipidemia (OSBPL10), beige fat biogenesis (CUL2), fatty liver disease and insulin resistance (PRTN3)." (PMID 40822952, 2025).
hepatitis B (6 papers, 2009 to 2024). "Further serologic tests, that is, hepatitis B, hepatitis C, Coombs test, anticardiolipin, anti-DNA, antinuclear, proteinase 3, and antineutrophil cytoplasmic antibodies (PR3-ANCA and cANCA), were negative." (PMID 25755670, 2015). "Subsequent studies were significant for a positive antinuclear antibody (ANA) and myeloperoxidase (MPO) antineutrophil cytoplasmic antibody (ANCA), negative proteinase 3 (PR3) ANCA, normal C3 and C4 complement protein levels, and negative hepatitis B and C serologies." (PMID 39650915, 2024).
multiple myeloma (6 papers, 2019 to 2024). "Multiple myeloma cell-derived IL-32γ significantly induced the production of the IDO1 in macrophages through proteinase 3 (PR3) and the downstream STAT3 and NF-κB pathways." (PMID 35003126, 2021).
influenza (5 papers, 2021 to 2024). An acute viral infection of the respiratory tract, occurring in isolated cases, in epidemics, or in pandemics; it is caused by serologically different strains of viruses (influenzaviruses) designated A, B, and C, has a 3-day incubation period, and usually lasts for 3 to 10 days. "In comparison, three patients had high activation of only a subset of influenza-connected genes PRTN3, LTF, PGLYRP1, DEFA1B, DEFA1, DEFA4, ELANE, and MPO." (PMID 34335605, 2021).
Insulin resistance (5 papers, 2019 to 2025). Increased resistance towards insulin, that is, diminished effectiveness of insulin in reducing blood glucose levels. "However, the downregulation of Prtn3 does not readily explain the reduced glucose tolerance in the DcnKO mice, based on the proposed stimulatory roles of Prtn3 in inflammation and insulin resistance." (PMID 30874564, 2019).
lung carcinoma (5 papers, 2004 to 2025). "AAT is the main inhibitor of neutrophil elastase and proteinase 3 and it has been reported that an imbalance between AAT and neutrophil elastase may predispose to lung cancer development." (PMID 15555067, 2004).
acute myeloid leukemia (4 papers, 2017 to 2024). Acute myeloid leukemia (AML) is a group of neoplasms arising from precursor cells committed to the myeloid cell-line differentiation. "In the case of acute myeloid leukemia (AML), our group has identified and characterized the leukemia-associated antigen, PR1, a nonameric, HLA-A2-restricted peptide derived from serine proteases proteinase 3 and neutrophil elastase." (PMID 38464203, 2024). "A potential immunotherapy approach for acute myeloid leukemia (AML) may be implemented through the application of HLA ligands, which could allow several established AML-related antigens, including PRTN3, to attract additional CD4+ T-cell epitopes." (PMID 37231509, 2023). "Our group has identified azurophil granule serine proteases, specifically cathepsin G (CG), neutrophil elastase (NE), and proteinase 3 (P3), as immunotherapeutic targets in acute myeloid leukemia (AML) and has developed immunotherapies that target these proteases." (PMID 29422892, 2017).
celiac disease (4 papers, 2022). An autoimmune genetic disorder with an unknown pattern of inheritance that primarily affects the digestive tract. "Clinical manifestations and double positivity for both myeloperoxidase (MPO) and anti-proteinase 3 (PR3) antibodies argued against the fact that that these findings were secondary to vaccination, cocaine abuse, or celiac disease." (PMID 35630067, 2022).
cryoglobulinemia (4 papers, 2013 to 2025). Cryoglobulinemia is a type of vasculitis that is caused by abnormal proteins (antibodies) in the blood called 'cryoglobulins.' At cold temperatures, these proteins become solid or gel-like, which can block blood vessels and cause a variety of health problems. "Cryoglobulinemia, anti-glomerular basement membrane (GBM) antibody, and anti-proteinase 3 (PR3) antibody were negative." (PMID 23617397, 2013).
heart failure (4 papers, 2013 to 2024). Inability of the heart to pump blood at an adequate rate to meet tissue metabolic requirements. "Proteinase 3 levels in the plasma are higher in chronic post-MI patients who later die or are re-admitted for heart failure compared to event-free survivors." (PMID 23731794, 2013). "This indicates that proteinase 3 may exacerbate heart failure and serve as a prognostic marker." (PMID 23731794, 2013).
Henoch-Schonlein purpura (4 papers, 2009 to 2024). "A punch biopsy of the medial leg demonstrated IgA vasculitis and autoimmune antibody analysis revealed increased levels of anti-proteinase 3 antibodies compared to anti-myeloperoxidase antibodies." (PMID 38957824, 2024).
type 1 diabetes (4 papers, 2016 to 2024). "In contrast, it has been recently reported that serum levels of elastase and proteinase 3, two proteins present in NETs, are significantly reduced in Type 1 diabetes patients and are correlated with a reduction in neutrophil counts." (PMID 28005949, 2016).
bacterial endocarditis (3 papers, 2008 to 2020). Endocarditis that is caused by an infection with a bacterial agent. "Subacute bacterial endocarditis (SBE) is rarely associated with positivity for anti-neutrophil cytoplasmic/proteinase-3 antibodies (c-ANCA/PR3)." (PMID 23268737, 2012). "Subacute bacterial endocarditis (SBE) occasionally exhibits positive cytoplasmic anti-neutrophil cytoplasmic antibody (c-ANCA) of the anti-proteinase-3 (PR-3) type." (PMID 23268737, 2012).
dementia (3 papers, 2022 to 2024). Loss of intellectual abilities interfering with an individual's social and occupational functions. "Overall, this could mean that higher PRTN3 levels are protective against amyloid pathology or that the lower levels of PRTN3 in dementia are a sign of synaptic loss." (PMID 35557837, 2022). "PRTN3 was lower in symptomatic AD (AD pathology diagnosis and dementia) compared to controls and asymptomatic AD (AD pathology diagnosis without dementia) in the Mayo Clinic temporal cortex data (not present in the Mount Sinai Brain Bank analysis)." (PMID 35557837, 2022). "Two genes (PRTN3 and PPDPF) were downregulated in dementia vs. NCI or MCI." (PMID 35557837, 2022). "Moreover, PRTN3 has been identified as a key protective factor across various cognitive states, including dementia, mild cognitive impairment, and no cognitive impairment, and is instrumental in cognitive decline." (PMID 38444019, 2024).
endothelial dysfunction (3 papers, 2015 to 2025). In vascular diseases, endothelial dysfunction is a systemic pathological state of the endothelium (the inner lining of blood vessels) and can be broadly defined as an imbalance between vasodilating and vasoconstricting substances produced by (or acting on) the endothelium. "Recruitment of neutrophils in glomeruli and the release of PRTN3 potentially lead to endothelial dysfunction." (PMID 25874235, 2015).
Hematuria (3 papers, 2012 to 2022). The presence of blood in the urine. "He had elevated level of proteinase 3-ANCA or C-ANCA with microscopic hematuria without significant kidney involvement in kidney biopsy." (PMID 31558999, 2019).
Mastoiditis (3 papers, 2013 to 2022). "We describe a patient with limited GPA with nasal lesions, otitis media, mastoiditis, sensorineural hearing loss, pachymeningitis, and positive cytoplasmic and proteinase-3 (PR-3) anti neutrophil cytoplasmic antibodies (ANCA)." (PMID 23984161, 2013).
myeloid leukemia (3 papers, 2011 to 2018). A clonal proliferation of myeloid cells and their precursors in the bone marrow, peripheral blood, and spleen. "Proteinase 3 is a myeloid cell-restricted serine protease abundantly expressed in azurophilic granules and is another promising myeloid leukemia-associated antigen." (PMID 22028726, 2011). "Firstly, vaccines against known antigens or epitopes which are peptide-based, such as PR1, a 9-mer peptide of proteinase-3 with high predicted binding and Wilm's Tumor (WT)-1 are shown to lead to specific T-cell responses in myeloid leukemia patients." (PMID 26378812, 2015). "It was originally reported that HLA-A∗0201-restricted proteinase 3 peptides induce CTLs that preferentially kill myeloid leukemia cells compared to normal marrow cells." (PMID 22028726, 2011). "Proteinase 3 has also been shown to be immunogenic, as proteinase-3-specific CTLs are induced in a substantial fraction of myeloid leukemia patients in vivo." (PMID 22028726, 2011).